SNORD114-9 (small nucleolar RNA, C/D box 114-9)
Synonyms: 14q(II-9)
Gene: Small nucleolar RNA gene on chromosome 14 (100,966,029 to 100,966,100, forward strand). Ensembl gene ENSG00000201240.
Gene Ontology:
Biological process: RNA processing
Cellular component: nucleolus
Homologues: Orthologues: chimpanzee SNORD114-9 (100% identical), macaque SNORD114-9 (100% identical). Paralogues in human: SNORD114-15 (93% identical), SNORD114-23 (93% identical), SNORD114-28 (93% identical), SNORD114-22 (92% identical), SNORD114-21 (90% identical), SNORD114-25 (90% identical), SNORD114-26 (89% identical), SNORD114-20 (86% identical), SNORD114-5 (86% identical), SNORD114-12 (85% identical), SNORD114-3 (85% identical), SNORD114-10 (83% identical), and 26 more.